SRD5A2 (steroid 5 alpha-reductase 2)
Description:
Catalyzes the irreversible stereospecific reduction of the delta 4,5 bond (double bond between carbons 4 and 5) of various 3-oxo steroids (3-keto steroids) producing their 5alpha dihydro-3-oxo forms. Converts testosterone into 5-alpha-dihydrotestosterone (DHT), the most active androgen in the prostate, as it is the preferred ligand for androgen receptor (AR) transactivation, making this reaction a key step in male sexual differentiation during development. Besides testosterone, it can also act on other steroids, including progesterone, producing metabolites with diverse roles. Hence, it plays a central role in sexual differentiation and androgen physiology.
Tractability: Small molecule: an approved drug acts on it; a structure with a bound ligand is known; a high-quality ligand is known; it belongs to a druggable protein family. Antibody: UniProt predicts a signal peptide or a membrane-spanning region. PROTAC: a small molecule that binds it is known.
Target class: Enzyme; Oxidoreductase
Chemical probes: finasteride
Gene: Protein-coding gene on chromosome 2 (31,522,480 to 31,580,941, reverse strand). Ensembl gene ENSG00000277893.
Subcellular location: Microsome membrane; Endoplasmic reticulum membrane
Pathways (Reactome):
Metabolism: Androgen biosynthesis
Gene Ontology:
Molecular function: 3-oxo-5-alpha-steroid 4-dehydrogenase (NADP+) activity; protein binding; testosterone dehydrogenase (NADP+) activity; 3-oxo-5-alpha-steroid 4-dehydrogenase activity; oxidoreductase activity, acting on the CH-CH group of donors
Biological process: androgen metabolic process; male gonad development; testosterone biosynthetic process; androgen biosynthetic process; cell-cell signaling; bone development; dibenzo-p-dioxin metabolic process; female genitalia development; hippocampus development; hypothalamus development; lipid metabolic process; male genitalia development; phthalate metabolic process; response to biphenyl; response to follicle-stimulating hormone; response to nutrient levels; response to peptide hormone; response to steroid hormone; response to testosterone; response to xenobiotic stimulus; steroid biosynthetic process; steroid catabolic process; steroid metabolic process
Cellular component: endoplasmic reticulum membrane; neuronal cell body; cell body fiber; membrane
Genetic constraint (gnomAD): Loss-of-function variants: 23 observed, 18.74 expected, observed/expected ratio (o/e) 1.23, 90% interval 0.88 to 1.72. The upper end of that interval is the gene's LOEUF score, 1.72, which puts it in group 6 of 6, group 1 being the genes least tolerant of losing a copy. Missense variants: 312 observed, 272.17 expected, observed/expected ratio (o/e) 1.15, 90% interval 1.04 to 1.26. Synonymous variants: 132 observed, 114.82 expected, observed/expected ratio (o/e) 1.15, 90% interval 1 to 1.33.
Homologues: Orthologues: chimpanzee SRD5A2 (99% identical), macaque SRD5A2 (95% identical), pig SRD5A2 (88% identical), rabbit SRD5A2 (85% identical), dog SRD5A2 (84% identical), rat Srd5a2 (78% identical), mouse Srd5a2 (75% identical), guinea pig SRD5A2 (56% identical), tropical clawed frog srd5a2 (55% identical), zebrafish srd5a2a (52% identical), zebrafish srd5a2b (44% identical), Caenorhabditis elegans F42F12.3 (36% identical), and 2 more. Paralogues in human: SRD5A1 (46% identical), TECR (28% identical), TECRL (22% identical).
Diseases named in the same sentence as SRD5A2 in open-access papers:
SRD5A2 is named in the same sentence as 65 diseases in open-access papers, as found by Europe PMC text mining. Sharing a sentence is not in itself a finding about the gene and the disease. The quoted sentences say what the papers report.
prostate carcinoma (31 papers, 2011 to 2026). A carcinoma that arises from epithelial cells of the prostate gland. "Nonetheless, the human SRD5A2 p.A49T variant has been implicated in several clinical pathologies, such as hypospadias, prostate cancer, and breast cancer." (PMID 40043094, 2025). "It’s reported that mutations in the type II steroid 5 alpha-reductase (SRD5A2) gene, which replaces valine with leucine at codon 89, reduced the risk of prostate cancer in Italian patients." (PMID 39351232, 2024). "SRD5A2 is highly expressed in androgen-sensitive tissues such as the prostate and the expression of SRD5A2 is associated with the progression of prostate cancer." (PMID 35196258, 2022). "BPH, androgenic alopecia, and prostate cancer are associated with high levels of DHT produced by SRD5A2 because of excessive AR signaling." (PMID 36344974, 2022). "Two polymorphisms rs523349 and rs9282858 have been identified in SRD5A2 gene, and their correlation with susceptibility to prostate cancer were reported previously." (PMID 28955247, 2017). "This epigenetic event, that cause the inhibition of SRD5A2 expression, is typically associated with the development of the hormone resistant form in prostate cancer." (PMID 28489571, 2017). "IntraprostaticSRD5A activity is regulated by the SRD5A2 gene, and polymorphisms of this gene (particularlySRD5A2 V89L and A49T) have been studied for associations with prostate cancer risk." (PMID 28472278, 2017). "Allelic variants in the SRD5A2 gene have also been associated with the development of androgen-dependent disorders, such as prostate cancer and PCOS." (PMID 26848581, 2016). "Elevated levels of SRD5A1 and SRD5A2 have been reported in prostate cancer and a correlation with the severity of the disease linked to increased dihydrotestosterone levels was documented." (PMID 22257483, 2012). "Mutations in the SRD5A2 gene have been linked to 5α-reductase deficiency and prostate cancer." (PMID 33110062, 2020). "Some disorders such as prostate cancer or hypospadias may be related with SRD5A2 gene polymorphisms." (PMID 26761946, 2016). "In the coding region, different genetic and molecular reports have shown that 2 well-known SRD5A2 gene polymorphisms or nsSNVs (rs9282858: c.145G>A, p.A49T; rs523349: c.265C>G, p.L89V; accessed on March 2, 2023) might be related to benign prostatic hyperplasia and possibly prostate cancer." (PMID 40043094, 2025). "In the network pharmacology analysis, 32 targets of Sappan lignum against prostate cancer were identified, including SRD5A2, which is closely related to the androgen receptor (AR)." (PMID 39318781, 2024). "To address and confirm the associations of SRD5A2 and ITGA11 protein levels with clinicopathological features, we used IHC assay on a prostate cancer tissue array, which contains tumor tissues from 42 patients." (PMID 35293897, 2022). "Human steroid 5α-reductase 2 (SRD5A2) is related to the progression of prostate cancer and benign prostatic hyperplasia." (PMID 35813821, 2022). "On the other hand, overproduction of DHT by SRD5A2 is associated with benign prostatic hyperplasia (BPH), androgenic alopecia, and prostate cancer due to excessive androgen receptor signaling." (PMID 33110062, 2020). "Immunohistochemical and polymerase chain reaction (PCR) analyses of human prostate tissues suggest that SRD5A1 and SRD5A2 levels change with prostate cancer development and progression." (PMID 22194926, 2011). "Also, in both human prostate cancer (DU-145) and HFDPC cells, the ethanolic Buebang 3 CMU extract (Et-BB3-CMU) suppressed SRD5A1, SRD5A2, and SRD5A3 expression—key pathways in hair loss—by 2-fold and 1.5-fold more than minoxidil and finasteride, respectively." (PMID 39519997, 2024). "A recent study has found that the methylation of SRD5A2 is related to the biochemical recurrence of prostate cancer, which may be applied to predict the BCR." (PMID 35813821, 2022).
prostate carcinoma (continued). "Finally, the “prostate cancer” pathway also includes DEGsSD that are relatively specific to the (human) prostate (SRD5A2, KLK2, NKX3-1 and CREB3L4), proto-oncogenes (EGFR, PDGFRA, PDGFRB, NRAS) and druggable candidates (PIK3CD, CTNNB1, PIK3CG, CDKN1A)." (PMID 34768937, 2021). "The goal of the study was to investigate possible association of some single nucleotide polymorphisms (SNPs) in the VDR gene (the FokI, BsmI, ApaI and TaqαI loci), and the CYP17 gene (the MspA1I locus), and 0 or 9 TA repeats in the SRD5A2 gene, and prostate cancer (PCa) among Lebanese men." (PMID 28240015, 2017). "Over-expression of SRD5A1 and SRD5A2 has been noted in breast and prostate cancer samples." (PMID 22257483, 2012). "In human prostate cancer cells (DU-145) and HFDPC cells, the SFE-4 extract significantly decreased the expression of SRD5A1, SRD5A2, and SRD5A3, an essential pathway involved in AGA." (PMID 38002174, 2023). "Lastly, there are already currently available clinical and genetic tools and technologies to evaluate prostate cancer outcomes based on HSD3B1, SLCO2B1, and SRD5A2 genotype and their relationships to disease, which will guide future biomarker-driven treatment." (PMID 37435458, 2022). "Specifically, half of the “prostate cancer” pathway DEGsSD had previously been referred to in the literature (AR, CDKN1A, CTNNB1, EGFR, KLK2, NKX3-1, PDGFRA, SRD5A2)." (PMID 34768937, 2021). "Our qRT-PCR analysis showed that DHT treatment resulted in an increased level of SRD5A1 mRNA, whereas it led to decreased levels of SRD5A2 and SRD5A3 mRNA in LNCaP prostate cancer cells." (PMID 22194926, 2011). "Through the analysis of seven datasets (TCGA, GSE30521, GSE4602, GSE55945, GSE69223 GSE104131, and GSE200879), we identified two upregulated genes (AMACR and GCNT1) and seven downregulated genes (TGFB3, SRD5A2, PGM5, HOXD10, AOX1, HSPB6, and SNAI2) in prostate cancer compared to normal tissue." (PMID 38374143, 2024). "Furthermore, half of the “prostate cancer” pathway DEGsSD are well described in the PCa literature (AR, CDKN1A, CTNNB1, EGFR, KLK2, NKX3-1, PDGFRA, SRD5A2), confirming that this is a pivotal pathway to specifically target clinical questions on canine PCa." (PMID 34768937, 2021). "The “prostate cancer” pathway also comprises genes that are relatively specific to the (human) prostate (CREB3L4, KLK2, NKX3-1 and SRD5A2), proto-oncogenes (EGFR, NRAS, PDGFRA and PDGFRB), and druggable candidates (CDKN1A, CTNNB1, EGFR, NRAS, PDGFRA, PDGFRB, PIK3CD and PIK3CG)." (PMID 34768937, 2021).
hypospadias (21 papers, 2007 to 2025). Hypospadias is the displacement of the urethral meatus on the ventrum of the penis. "This cluster explores topics such as “46, XY disorders of sex development,” “receptor gene,” and “srd5a2,” shedding light on the causes of sexual development abnormalities and genetic mechanisms behind hypospadias." (PMID 40303952, 2025). "Mutations in SRD5A2 result in variable degrees of hypospadias, sometimes with micropenis and undescended testes, still placing these cases within the TDS continuum." (PMID 41595460, 2025). "Loss-of-function mutations in the 5α-reductase gene (SRD5A2) cause severe hypospadias in male individuals." (PMID 39642224, 2024). "Our results indicate that SRD5A2 and AR genes are two top candidate genes associated with 46, XY hypospadias in Chinese patients." (PMID 34276780, 2021). "Inactivating mutations of the 5α-steroid reductase type-2 (SRD5A2) gene result in a broad spectrum of masculinization defects, ranging from a male phenotype with hypospadias to a female phenotype with Wolffian structures." (PMID 25077171, 2014). "Moreover, in one Chinese patient with hypospadias, sequencing revealed the compound mutation p.G203S/p.Q6X in the SRD5A2 gene." (PMID 35331321, 2022). "Two of three hypospadias cases had pathogenic variants in SRD5A2 (case 51) and AR (case 94)." (PMID 34367232, 2021). "The phenotypic spectrum associated with 46,XY DSD due to autosomal recessive mutations in the SRD5A2 gene is broad, varying from normal female external genital appearance to micropenis, isolated hypospadias, or micropenis associated with hypospadias of varying severity." (PMID 25077171, 2014). "Their findings indicated that SRD5A2 negatively regulated miR-1199-5p and significantly affected key cellular processes in hypospadias, highlighting the critical role of miR-1199-5p in the development of the condition." (PMID 39624466, 2025). "A large-scale whole-exome sequencing (WES) study revealed that approximately 27% of severe hypospadias cases carried rare damaging variants in genes critical to testosterone synthesis and signaling, including AR, NR5A1, and SRD5A2." (PMID 41595460, 2025). "Gene mutations in androgen receptor (AR), 5-α reductase (SRD5A2), and steroidogenic factor 1 (NR5A1) are linked to hypospadias formation." (PMID 39642224, 2024). "There were also decreases in the expressions of the enzymes Cyp11a1, Hsd3b, Scarb1 and Star, and the expressions of AR and Srd5a2 were decreased only in the testes of rats with hypospadias." (PMID 39728417, 2024). "The steroid 5α-reductase 2 (SRD5A2) and androgen receptor (AR) genes are two androgen dependent genes that were widely evaluated in hypospadias." (PMID 34276780, 2021). "Among the Chinese population, SRD5A2 and AR dysfunction have been discovered in some patients with hypospadias." (PMID 34276780, 2021). "It was also noted that 11 mutations in SRD5A2 gene, 6 mutations in AR gene, and one variant in MID1 gene in this study were also correlated to abnormal male genital development and hypospadias." (PMID 34276780, 2021). "It is necessary to examine preputial tissues from normal healthy individuals to compare the mRNA expression levels of CYP1 family genes and the DNA methylation level of SRD5A2 with those in preputial tissues from individuals with hypospadias." (PMID 29080015, 2018). "Variants in the AR gene, such as CAG and GGN repeat polymorphisms, and in the 5-α reductase 2 gene (SRD5A2), which converts testosterone (T) to the more potent dihydrotestosterone (DHT) have been associated with hypospadias." (PMID 17343741, 2007). "Furthermore, a significantly negative correlation was detected between the mRNA expression levels of the CYP1 family genes and the methylation level of the − 221 Sp1 site of SRD5A2 in hypospadias." (PMID 29080015, 2018).
hypospadias (continued). "The expression level of SRD5A2 mRNA in the hypospadias group was similar to that in the phimosis group; however, the AR mRNA expression level in the phimosis group was found to be higher than that in the hypospadias." (PMID 29080015, 2018). "We found a significant positive association of mRNA expression level and a negative association of methylation level of the SRD5A2 gene with the mRNA expression levels of CYP1 family genes in the preputial tissue of patients with hypospadias." (PMID 29080015, 2018). "However, we found significant correlations of CYP1 family mRNA expression levels with the SRD5A2 mRNA expression level and SRD5A2 promoter DNA methylation levels in the hypospadias patients, which suggests the involvement of chemical exposure in the onset of hypospadias." (PMID 29080015, 2018). "The significant positive association of mRNA expression level and the negative association of methylation level of the SRD5A2 gene with the mRNA expression levels of CYP1 family genes in the preputial tissue seem to indicate the chemical exposure of patients with hypospadias." (PMID 29080015, 2018). "A recent study determined that miR-1199-5p targets SRD5A2, influencing EMT transformation and promoting the development of hypospadias, highlighting the crucial role of EMT through miR-1199-5p in this condition." (PMID 39624466, 2025). "Additionally, epigenetic alterations can be involved in hypospadias development such as the methylation of the AR gene, the SRD5A2 gene, or CpG sites, determining the use of DNA methylation patterns to identify and evaluate new candidate genes that may be involved in the etiology of hypospadias." (PMID 37238140, 2023). "A positive correlation also was seen between the mRNA expression level of SRD5A2 and that of CYP1A1 in the hypospadias group." (PMID 29080015, 2018). "A significantly positive correlation was found between the mRNA expression level of SRD5A2 and that of CYP1B1 in the hypospadias group." (PMID 29080015, 2018). "Polymorphisms, mutations, and epigenetic changes in the AR, CYR61, HSD17B3, HSD3B1, MAMLD1, SRD5A2, and STARD3 have been associated to hypospadias risk in severe types of hypospadias that have not been found in mild hypospadias." (PMID 33425810, 2020). "A significantly negative correlation was detected between the mRNA expression and methylation levels of SRD5A2 in the hypospadias group particularly at the − 221 Sp1 site, whereas no such negative correlation was detected in the phimosis group." (PMID 29080015, 2018). "Positive correlations (P < 0.001) between the mRNA expression levels of the CYP1 family and SRD5A2 were found in patients with hypospadias but not in those with phimosis." (PMID 29080015, 2018). "Negative correlations were found between the methylation level of SRD5A2, especially at the − 221 Sp1 site, and the CYP1 family mRNA expression levels (CYP1A1, p = 0.002; CYP1B1, p = 0.007) in hypospadias patients, but not in phimosis patients." (PMID 29080015, 2018).
benign prostatic hyperplasia (12 papers, 2015 to 2025). A non-cancerous nodular enlargement of the prostate gland. "Among these genes, steroid 5α-reductase 1 (SRD5A1) and steroid 5α-reductase 2 (SRD5A2) encode 5α-reductase type 1 and type 2, respectively, which are involved in testosterone metabolism and have been associated with an increased risk of prostatic hyperplasia." (PMID 38778357, 2024). "Recent data indicate that stromal SRD5A2 promotes prostate growth in Benign Prostatic Hyperplasia (BPH) via a paracrine WNT5A-LEF1-IGF1 signaling axis." (PMID 41514571, 2025). "DHT is known to be the most important male hormone for prostatic hypertrophy, and SRD5A2 regulates the process of DHT formation from testosterone." (PMID 33803357, 2021). "Finasteride and dutasteride, as SRD5A2 inhibitors, are widely used antiandrogen drugs for benign prostate hyperplasia." (PMID 33110062, 2020). "The dual SRD5A1 and SRD5A2 inhibitor, dutasteride, and the selective SRD5A2 inhibitor, finasteride, are extensively used in the treatment of benign prostatic hyperplasia, whereby they decrease local generation of DHT." (PMID 26574953, 2016).
androgen insensitivity syndrome (5 papers, 2012 to 2025). Androgen insensitivity syndrome (AIS) is a disorder of sex development (DSD) characterized by the presence of female external genitalia, ambiguous genitalia or variable defects in virilization in a 46,XY individual with absent or partial responsiveness to age-appropriate levels of androgens. "However, molecular analysis of SRD5A2 gene variants is generally required to confirm the diagnosis, since the hormonal and clinical profiles of 5ARD2 often overlap with other conditions, including androgen insensitivity syndrome, 17 beta-hydroxylase deficiency and defects in the NR5A1 gene." (PMID 31885560, 2019).
Infertility (4 papers, 2007 to 2025). "This deficiency in SRD5A2 production is suggested to contribute to hybrid infertility by impairing AR signal transduction and disrupting sperm physiology." (PMID 40075943, 2025). "This suggests that a deficiency in SRD5A2 production in the epididymis may result in hybrid infertility, as it can subsequently cause incomplete AR signal transduction and altered spermatozoa physiology." (PMID 40075943, 2025). "This study explores the infertility observed in hybrid male cattle–yaks, focusing on the roles of the androgen receptor (AR) and 5α-reductase isoform 2 (SRD5A2) in the epididymis." (PMID 40075943, 2025). "Lycium barbarum caused an up-regulation in the expression of CYP19A1, CYP17A1, AR, and SRD5A2, which in turn increased the level of serum testosterone to combat infertility." (PMID 40149961, 2025). "We found variants in genes categorized into isolated infertility (AR and CFTR), reproductive disorders (SRD5A2), and endocrine disorders (LHCGR and CYP21A2)." (PMID 39830005, 2024).